TNF (tumor necrosis factor)
Diseases named in the same sentence as TNF in open-access papers (continued):
Sharing a sentence is not in itself a finding about the gene and the disease.
Hyperglycemia (continued). "In addition, oscillatory hyperglycemia as routinely found in most patients, causes more acute increases in plasma concentrations of pro-inflammatory cytokines including IL-6, IL-18, and TNF-α, as compared to chronic hyperglycemia." (PMID 21629436, 2010). "Hyperglycaemia up-regulated the expression of several proinflammatory genes, including those encoding for IL-1β and TNF-αin vitro, the latter gene via increased recruitment of nuclear factor kappa B (NF-κB) p65 to the TNF-α promoter." (PMID 18290856, 2008). "In PCOS, stimulation of reactive oxygen species (ROS) generation from mononuclear cells (MNCs) by hyperglycaemia may play a role in inflammation through the release of TNFα from circulating MNCs." (PMID 17919323, 2007). "First, hyperglycemia-induced oxidative stress leads to excessive reactive oxygen species production and activation of the NF-κB signaling cascade, promoting secretion of IL-6, TNF-α, and MCP-1, which further recruit neutrophils and perpetuate kidney inflammation." (PMID 41492002, 2026). "Additionally, humoral factors, including pro-inflammatory cytokines, such as tumor necrosis factor-alpha (TNF-α), interleukin-6 (IL-6), and interleukin-1 beta (IL-1β), further exacerbate hyperglycemia by impairing insulin signaling and increasing hepatic glucose output." (PMID 40868089, 2025). "After observing that certain cytokines and chemokines were upregulated in the combined challenge of GBS infection and hyperglycemia, while TNF-α, MCP-1 and MIP-1β were downregulated under these conditions, we investigated whether the chemoattraction of immune cells would be affected." (PMID 40746553, 2025). "Among the various inflammatory mediators, IL-6 and TNF-α have demonstrated consistent associations with early pregnancy glycemic alterations and have shown promise as predictive biomarkers of GDM prior to the onset of hyperglycemia detectable by oral glucose tolerance testing." (PMID 40722699, 2025). "Furthermore, hyperglycemia induces a pro-inflammatory microenvironment characterized by elevated levels of systemic markers such as IL-6 and TNF-α, which correlate with disrupted bone turnover and increased skeletal fragility through mechanisms distinct from direct glucose-mediated effects." (PMID 40276745, 2025). "Moreover, hyperglycemia exposure triggered chronic low-grade inflammation by TNF-α signaling." (PMID 40017691, 2025). "Hypertriglyceridemia and hyperglycemia, which are key components of the TyG index, activate macrophages and promote the release of pro-inflammatory cytokines such as interleukin-6 (IL-6) and tumor necrosis factor-alpha (TNF-α), driving chronic low-grade systemic inflammation." (PMID 40421215, 2025). "Sleep disturbances and insomnia can increase inflammatory cytokines (hs-CRP, tumor necrosis factor, interleukin 6) and enhance the hypothalamic-pituitary-adrenal activity, leading to reduced β-cell function, increased insulin resistance, and contributing to hyperglycemia." (PMID 41114778, 2025). "Furthermore, macrophages, in response to hyperglycemia, downregulate their Fcγ receptor, resulting in a defect in phagocytosis and antigen presentation while enhancing the production of inflammatory cytokines (e.g., TNFα, IL1β)." (PMID 40868889, 2025). "We demonstrated that the microvascular morphological changes of pancreas are highly correlated with progressive inflammatory infiltration and proinflammatory cytokine production, including TNF-α, IL-1β, and IL-6, which could lead to β cell decline and hyperglycemia with age." (PMID 40066372, 2025). "The evidence showed hyperglycemia to be associated with unfavorable treatment outcomes; altered counts and functioning of dendritic cells, monocytes, and CD4+ T cells; and changes in cytokine levels (mainly INF-γ, IL-17, IL-1β, IL-2, IL-6, IL-10, and TNF-α) in patients with DM-TB." (PMID 39981106, 2024).
Hyperglycemia (continued). "Therefore, and contrary to what we expected, a double inflammatory stimulus by severe hyperglycemia and S. agalactiae infection resulted in a weaker inflammatory profile, despite each one of these insults alone led to increased TNF-α and IL-6 production in comparison to normoglycemia." (PMID 36982317, 2023). "In addition, hyperglycemia induces certain inflammatory factors [tumor necrosis factor-α (TNF-α), interleukin-6 (IL-6), C-reactive protein (CRP), etc.] and inflammatory reactions, all of which cause varying degrees of damage to cardiomyocytes, blood vessels, and even the heart." (PMID 37448666, 2023). "Hyperglycemia is closely related to the excess generation of reactive oxygen species (ROS) and oxidative stress which can up-regulate the levels of inflammatory factors including tumor necrosis factor-alpha (TNF-α), interleukin-6 (IL-6) and reduces the level of interleukin 10 (IL-10)." (PMID 37396948, 2023). "A statistically significant increase in TNFα secretion, the ‘classical player’ of the acute-phase immune response, could only be detected 6 h after the stimulation with Hb-Hp complexes in hyperglycemia, regardless of the present haptoglobin variant." (PMID 35163309, 2022). "A statistically significant increase in TNFα secretion could only be detected 6h after the stimulation with Hb-Hp complexes in hyperglycemia, regardless of the present haptoglobin variant." (PMID 35163309, 2022). "Chronic exposure to pro-inflammatory cytokines such as TNF-α, IL-1β and IL-6 activates the signaling proteins that block the activation of the insulin signaling cascade in the target organs of insulin, including skeletal muscle, adipose tissue and liver, leading to hyperglycemia." (PMID 34201653, 2021). "Our recent study found a set of 17 circulating KRIS proteins that were strongly associated with progression to ESKD17, In this in vitro HUVECs study, we examined whether intracellular and extracellular levels of the KRIS proteins were regulated by exposure to high levels of TNFα and hyperglycemia." (PMID 34045516, 2021). "Hyperglycemia can induce nonenzymatic protein glycation, and the resulting advanced glycation end products (AGEs) have been shown to stimulate macrophages, causing them to release cytokines such as IL-6 and TNF-α, as well as C-reactive protein." (PMID 34068221, 2021). "However, how TNFα mediated the telomere-mitochondria axis in hyperglycemia remains unclear and has yet to be further explored." (PMID 32454945, 2020). "Hyperglycaemia, alone can trigger inflammation by activating the pro-inflammatory transcription factor nuclear κB (NF-κB), resulting in an increased inflammatory chemokine and cytokine release including interleukin-6 (IL-6), interleukin-8 (IL-8), and tumor necrosis factor-α (TNF-α), among others." (PMID 32517031, 2020). "Persistent hyperglycemia triggers expression of various proinflammatory cytokines and chemokines, including interleukin-6 (IL-6), interleukin-8 (IL-8), interleukin-1α (IL-1α), and tumor necrosis factor-alpha (TNF-α, which in turn leads to an increase in the inflammatory response." (PMID 33147748, 2020). "Finally, individuals with hyperglycemia were found to have higher levels of inflammatory cytokines such as interleukin-6 and tumor necrosis factor-alpha and these inflammatory factors may also have some adverse effects on muscle mass." (PMID 33046005, 2020). "Moreover, according to the cytokine kit analysis, the VEGF, TNF-α, IL-18 and IL-1β levels in rat plasma demonstrated similar trends, which also supported that H3 relaxin lessened the inflammatory activity induced by hyperglycemia." (PMID 33584279, 2020). "However, these cytokines are produced after the hyperglycemic peak, and thus we focused on the relationship between vagal modulation of hyperglycemic and TNF and whether the vagus nerve controls hyperglycemia by regulating TNF." (PMID 30700738, 2019).
Hyperglycemia (continued). "However, the high expression of TNF-α due to long-term hyperglycemia and advanced glycation end products (AGEs) could decrease MSCs’ proliferation ability and increase MSC apoptosis via the caspase pathway and p38 MAPK pathway." (PMID 31780804, 2019). "In particular, iatrogenic hyperglycemia can lead to impaired wound healing, neuronal dysfunction, increased production of the inflammatory cytokines interleukin-6 (IL-6) and tumor necrosis factor-α (TNF-α), inhibition of leukocyte function, vasculitis, and ultimately a poorer clinical outcome." (PMID 31998762, 2019). "Therefore, it was speculated that the activation of TNF signaling pathway might be a reason for the occurrence of hyperglycemia in CHD patients." (PMID 29214180, 2017). "The present study demonstrated that short-term (2-week) hyperglycemia does not cause axonal degeneration but instead exerts axonal protection against TNF-induced optic nerve degeneration as shown by morphometric analysis of light microscopic as well as by electron microscopic study results." (PMID 26578885, 2015). "Therefore, in the present study, we investigated whether short-term hyperglycemia prevents TNF-induced optic nerve degeneration and examined the role of autophagy in this axon change process." (PMID 26578885, 2015). "Additionally, hyperglycemia may stimulate the production of inflammatory cytokines, such as IL-6, IL-1, and tumor necrosis factor alpha (TNF-α), by increasing the levels of peroxides and free radicals and inducing inflammation." (PMID 23533689, 2013). "In this regard, it is possible that the low AR levels due to hyperglycemia, high TNFα levels and low testosterone levels, apart from conferring protection against PCa development could also act as a mechanism for driving the prostate cells towards some degree of androgen independence." (PMID 24058525, 2013). "Treatment with the isolated metabolites, particularly Pheophytin a, significantly mitigated hyperglycemia, upregulated insulin receptor and GLUT4 expression, activated the PI3K/AKT signaling pathway, and suppressed TNF-α mediated inflammation." (PMID 41964775, 2026). "We observed that the dual stimulus of infection and hyperglycemia downregulated the gene expression of MCP-1 and TNF-α, consistent with the results from the secretion assay." (PMID 40746553, 2025). "In vitro mechanistic studies revealed IL17 and hyperglycemia synergistically upregulated the expression of proinflammatory and pro-fibrotic genes, including IL6, TNFα, and TGFβ, in renal epithelial cells." (PMID 40868889, 2025). "Hyperglycemia activates macrophages via pathways involving TGF-β1, MCP-1, tumor necrosis factor-alpha (TNF-α), and IL-1β, leading to the upregulation of NF-κB and subsequent renal injury." (PMID 40598250, 2025). "The combined stimulus of hyperglycemia and GBS resulted in reduced placental expression of TLR-2, TNF-α, MCP-1, and MIP-1β, thereby impairing the chemotaxis of IVMC, monocytes, and NK cells." (PMID 40746553, 2025). "The CoPP-induced HO-1 also led to downregulations of IL-1β and TNFα, two inflammatory markers known to be expressed in RPE cells under hyperglycemia." (PMID 39857426, 2025). "This impaired recognition likely contributes to the observed downregulation of key chemotactic mediators — TNF-α, MCP-1, and MIP-1β — observed when both infection and hyperglycemia are present." (PMID 40746553, 2025). "Hyperglycemia was also shown to enhance SARS-CoV-2 replication and the production of proinflammatory cytokines such as TNF-α and IL-6 in monocytes in vitro." (PMID 37934800, 2024). "Although our studies did not attempt to study how hyperglycemia and TNF-α aid CysLTR1-associated changes in HRECs, it may be speculated that hyperglycemia and TNF-α–mediated stress might elevate LTE4, as also observed in preclinical models and diabetic subjects." (PMID 39504050, 2024).
Hyperglycemia (continued). "In other studies, but not in accordance with the current findings, increases during hypoglycemia has also been described for TNF-α, Il-8 and VEGF-A, while TNF-α and IL-18 have been demonstrated to increase during hyperglycemia." (PMID 37400734, 2023). "In turn, the increased glucose metabolism imposed by sustained hyperglycemia seems to enhance SARS-CoV-2’s entry and subsequent replication, as well as exacerbated immune responses such as tumor necrosis factor-α, interleukin (IL)-1β, and IL-625,26." (PMID 38123659, 2023). "Molecular pathways such as the inhibition of NF-κB phosphorylation and NF-κB nuclear translocation, upregulation of TGF-β, TLR-4, TNF-α, ZO-1, GLP-2, and TGF-β1 by phytoconstituents can reduce AGEs and hyperglycemia-related complications." (PMID 37108833, 2023). "However, whether TNF-α inhibitors improve hyperglycemia and DM is controversially discussed." (PMID 37047569, 2023). "Mitochondria can produce ROS through a variety of pathophysiological stimuli, including angiotensin II, tumor necrosis factor α (TNF-α), integrin ligation, hyperglycemia, oxidized low-density lipoprotein (LDL), and superoxide from NADPH oxidase." (PMID 37047024, 2023). "In accordance with the ROS results, the TUNEL staining and IL-6/TNF-α results also showed that KDM3A knock-out evidently alleviated sustained apoptosis and inflammatory responses induced by hyperglycemia." (PMID 35571189, 2022). "In obese diabetic ob/ob mice, COS supplementation improved BW gain, dyslipidemia, and hyperglycemia, as well as regulated a variety of adipokine expression, shown by an increase in adiponectin and a decrease in RBP4, resistin, TNF-α, and IL-6." (PMID 36547931, 2022). "It has been shown that 6-gingerol has renoprotective effects in diabetic rats due to its ability to regulate urea and creatinine levels, inhibiting oxidative stress, hyperglycemia, and inflammatory markers such as CRP, IL-6, IL-1, and TNF-α." (PMID 36557312, 2022). "The expression of NT5DC3 declined significantly during hyperglycemia, while that of other proteins, such as p-PI3K, p-AKT, p-mTOR, IL-1β, and TNF-α, was substantially higher." (PMID 36553697, 2022). "In this analysis, levels of IL-10, IL-10/TNF-α ratio, and CXCL10 were found to be independent predictors of stress hyperglycemia as defined by a SHR of more than 1.14." (PMID 36059840, 2022). "Vascular endothelial cells activated by hyperglycemia and/or AGE express cell adhesion molecules (CAM) by stimulating cytokines, tumor necrosis factor-alpha (TNFα), and interleukin-1 (IL-1)." (PMID 36005129, 2022). "The first-trimester trophoblast exposed to hyperglycemia (25 mM) induces the release of exosomes which in turn induces the endothelial release of IL-4, IL-6, IL-8, INF-γ, and TNF-α." (PMID 34360849, 2021). "The communication was mediated by ligand TNF-α and its two receptors, TNFR1 and TNFR2, which were elevated by hyperglycemia in microglia." (PMID 34434927, 2021). "First of all, we analyzed mRNA levels of EMT and CSC inducers—namely, the cytokines IL-6, IL-8, TNF-α and TGFβ-1—in PDEC exposed to M1-polarized macrophages and/or hyperglycemia." (PMID 34064969, 2021). "Firstly, hyperglycemia in T2DM patients increases a variety of signaling pathways and upregulates the expression of inflammatory factors such as IL-6 and TNF-α." (PMID 33456672, 2020). "Furthermore, Hyperglycemia could also increase inflammatory cytokine (including tumor necrosis factor‐α [TNF‐α], interleukin‐6 [IL‐6], and interleukin‐18 [IL‐18]) by an oxidative stress mechanism in human, suggesting hyperglycemia triggers inflammatory response." (PMID 32697441, 2020). "Hyperglycemia condition in T2DM can lead to increased ROS production which upregulates TNF-α expression and induces cardiomyocyte apoptosis via increasing the expression of the Fas." (PMID 32509880, 2020).
Hyperglycemia (continued). "Moreover, persistent hyperglycemia results in the glycosylation of myelin protein, which changes the antigenicity of neurons, promoting activation of glial cells, leukocyte infiltration, and release of inflammatory cytokines, including TNF-α and IL-1β, leading to neuroinflammation." (PMID 32659952, 2020). "In the subjects with hyperglycemia, a significant positive correlation is observed between LTL and mtDNAcn, which is probably mediated by TNFα." (PMID 32454945, 2020). "TNFα plays a cardinal role in oxidative stress and inflammation; in PCOS, production of TNFα is induced by hyperglycemia and hyperandrogenemia." (PMID 32133054, 2019). "Canagliflozin administration to NA/STZ/Suc mice normalized hyperglycemia as well as elevated renal mRNA of collagen 1a1, 1a2, CTGF, TNFα and MCP-1." (PMID 31367234, 2019). "Hyperglycemia and ROS production also promote TLR-2 and TLR-4 activation, with release of TNF-α, IL-1β, IL-8, monocyte chemoattractant protein (MCP-1), vascular cell adhesion molecule 1 (VCAM-1), intracellular adhesion molecule 1 (ICAM-1)." (PMID 31835864, 2019). "We have also previously reported that knockdown of CB1R signaling effectively attenuates the hyperglycemia-induced upregulation of c-Jun, TGF-β1, IL-6, and TNF-α in vitro and in vivo." (PMID 30642005, 2019). "Tumor necrosis factor-α (TNF-α) and interleukin (IL)-1β have been involved in apoptosis of pancreatic β-cells, decreasing insulin secretion with the consequent hyperglycemia characteristic of T2DM." (PMID 28225996, 2017). "The biological function of PTPN2 is believed to vary in response to proinflammatory stimuli such as interferon-gamma (IFN-γ), tumor necrosis factor (TNF-α), hyperosmotic stress, or hyperglycemia." (PMID 27995146, 2016). "In the present study, we demonstrated that an increased level of miR-15b and/or miR-16 in REC resulted in decreased signaling of TNFα and SOCS3, indicating the role of the microRNAs as regulators of these cytokine pathways in response to hyperglycemia." (PMID 25888955, 2015). "For instance, hyperglycaemia-induced reactive oxygen species production resulted in activation of PKC and NFκB which, in turn, induced proinflammatory cytokines, TNFα and IL1β." (PMID 25883984, 2015). "Characteristically, this state of inflammation permits the secretion of pro-inflammatory cytokines particularly IL-6, tumour necrosis factor (TNF)-α and CRP which are actively involved in insulin resistance and hyperglycaemia." (PMID 26512338, 2015). "The key markers of oxidative stress and inflammation such as inflammatory cytokines (IL-1β, IL-6, and TNF-α) and immunoregulatory cytokines (IL-4 and IFN-γ) were increased in kidneys along with significant hyperglycemia." (PMID 25295146, 2014). "OPN expression is upregulated by proinflammatory cytokines such as tumor necrosis factor-α (TNF-α) and transforming growth factor-β (TGF-β), as well as by hypoxia and hyperglycemia." (PMID 24871103, 2014). "Our results suggest that hyperglycemia down-regulates CD33 expression and triggers the spontaneous secretion of TNF-α by peripheral monocytes." (PMID 22500980, 2012). "In cultured human vascular endothelial cells, Liraglutide inhibited the expression of tumor necrosis factor-α (TNF α) and the hyperglycemia-mediated induction of VCAM-1 and PAI-1." (PMID 22577369, 2012). "However, it remains unknown whether the dynamic changes of circulating TNF-α, IL-6 and nitrotyrosine induced by postchallenge hyperglycemia might be associated with CAD in patients without previously recognized T2DM." (PMID 22397368, 2012). "Mechanisms proposed to account for pericyte apoptosis include rapid fluctuations of blood glucose, increased Bax expression during hyperglycemia, increased AGE formation, and TNF-α production." (PMID 20300563, 2010).